BDNF (brain derived neurotrophic factor)
Diseases named in the same sentence as BDNF in open-access papers (continued):
Sharing a sentence is not in itself a finding about the gene and the disease.
epilepsy (continued). "Accumulating evidence suggest that BDNF decreases KCC2 expression and function in several adult brain regions, under different neuropathological conditions including epilepsy, traumatic brain injury, and nociception." (PMID 35874836, 2022). "However, it is not clear whether the decrease in BDNF levels causes the epileptogenesis or isonly a concomitant phenomenon of epilepsy." (PMID 34899313, 2021). "SVHRP upregulated the mRNA and protein levels of BDNF and NPY, providing a potential candidate for epilepsy treatment." (PMID 33825777, 2021). "So the results suggested that the proBDNF has another pathway except for transforming into BDNF, which also can suppress epilepsy." (PMID 34899313, 2021). "Our ongoing study will increase the sample size and validate the role of ADORA2A, BDNF, and NTRK2 in epilepsy." (PMID 33262686, 2020). "Hippocampal BDNF expression and CREB activity have both been shown to be upregulated in epilepsy and downregulated in stress and depression." (PMID 32179735, 2020). "Several genes of particular interest to the field of epilepsy are listed with the degree of FC from DMSO+Water vs. DMSO+BDNF and the FC of DMSO+BDNF vs. WP1066 + BDNF." (PMID 31455240, 2019). "After miR-103a inhibitors interfered with epilepsy rats, there showed decreased expression of miR-103a and GFAP, increased expression of BDNF and decreased number of apoptotic neuron as well as increased number of surviving neurons." (PMID 31049031, 2019). "A large set of diametric psychopharmacological patterns emerged from the analyses, with regard to the pathways involving BDNF, PI3K, the NMDA and mGlur5 receptors, kynurenine, agmatine, the endocannabinoid anandamide, epilepsy and electroconvulsive therapy." (PMID 31548888, 2019). "Our results indicate a possible role for BDNF and IGF-1 in regulation ANS functions and cerebral autoregulation in patients with epilepsy." (PMID 30524358, 2018). "Correlation analysis of BDNF and IGF-1 levels with demographic variables, autonomic functions, and cerebral autoregulation parameters in patients with epilepsy and controls." (PMID 30524358, 2018). "We propose that reduced serum levels of BDNF and IGF-1 are consistent with the hypothesis that a deficit in these neurotrophic factors may contribute to the structural and functional alterations of the brain underlying the neurodegenerative process related to chronic and severe epilepsy." (PMID 30524358, 2018). "Recent studies have found that BDNF and IGF-1 can modify the functions of the central nervous system (CNS) that are involved in neurological and psychiatric diseases, including epilepsy." (PMID 30524358, 2018). "Evidence from animal studies has shown that BDNF and IGF-1 also play a partial role in the pathophysiology and epileptogenesis of epilepsy." (PMID 30524358, 2018). "Localized delivery of FGF-2 and brain-derived neurotrophic factor (BDNF) to the lesioned hippocampus increases neurogenesis and reduces epileptogenesis in a rat model of epilepsy." (PMID 24735639, 2014). "Finally, it normalizes the overactive BDNF‐pAKT‐CREB signaling pathway, a key driver of neuronal excitability and epileptogenesis that is upregulated in epilepsy models, and whose inhibition reduces seizure severity." (PMID 41574686, 2026). "However, in TLE, the abnormal upregulation of BDNF expression may lead to neuronal overexcitation, lower the seizure threshold, and exacerbate the progression of epilepsy.This “double-edged sword” effect makes the role of the BDNF/TrkB signaling pathway in epilepsy complex." (PMID 41020886, 2025). "However, other authors have described that BDNF downregulates KCC2 after injury and mediates the decrease in KCC2 observed in neurological diseases, such as epilepsy, neuropathic pain, and spasticity." (PMID 39337430, 2024).
epilepsy (continued). "Here, we studied the correspondence of the expression of BDNF, NSE, VILIP-1, and S100B in the blood (serum and PBMCs) with the in vivo content in the hippocampuses of patients with drug-resistant epilepsy using biosamples obtained during neurosurgical operations." (PMID 38203674, 2023). "The core EpiPro promoter consists of the following response elements upregulated in epilepsy: nuclear factor of activated T-cells (NFAT); early growth response protein (EGR); calcium response elements (CaRE) from brain-derived neurotrophic factor (BDNF); and cAMP response elements for CREB." (PMID 37833914, 2023). "We found that BDNF levels in the hippocampus from TMEV-infected mice with seizures was increased at the onset of acute seizures and continued to increase during the peak of acute seizure as well as in latent and chronic phases of epilepsy." (PMID 35874836, 2022). "Currently, it is known that BDNF is involved in the event of aberrant synaptic plasticity called mossy fiber sprouting, observed in temporal lobe epilepsy (TLE), which is one of the most common types of epilepsy in adults." (PMID 34086671, 2021). "Evidently, alterations in expression of neurotrophic factors, such as BDNF and GDNF, have been observed in epilepsy and neuropsychiatric disorders, and aberrant expression of these factors may be amenable to stem cell therapy." (PMID 33815100, 2021). "Synthesizing these findings, we speculated that miR-134 upregulation in epilepsy, by restricting CREB translation, serves as a posttranscriptional control element counteracting the BDNF upregulation." (PMID 32179735, 2020). "There is a strong body of evidence suggesting that BDNF signaling through its TrkB receptor contributes in a major way to the development of TLE, as suggested by animal models of epilepsy and their potential relationship to human epilepsy brain pathology." (PMID 31455240, 2019). "There was a significant decrease in serum levels of both BDNF and IGF-1 in patients with epilepsy." (PMID 30524358, 2018). "However, the role of BDNF and IGF-1 in epilepsy in humans has been explored only to a limited extent." (PMID 30524358, 2018). "Serum levels of BDNF and IGF-1 in patients with epilepsy and controls." (PMID 30524358, 2018). "Correlation analysis of BDNF and IGF-1 between the seizure semiology in the patients with epilepsy." (PMID 30524358, 2018). "However, an understanding of the pathophysiological role of reduced serum levels of BDNF and IGF-1 in patients with epilepsy requires further studies in humans." (PMID 30524358, 2018). "Long-term epilepsy and severe epilepsy, particularly temporal lobe epilepsy, may perturb BDNF and IGF-1 signaling, which contribute to autonomic dysfunction and impaired cerebral autoregulation in patients with epilepsy." (PMID 30524358, 2018). "This underscore BSN, BDNF and NTRK2 interconnection in epilepsy, corroborated in this study." (PMID 24278214, 2013). "However, the molecular mechanisms connecting BDNF with epileptogenesis and epilepsy are not well elucidated." (PMID 38006577, 2024). "However, a meta-analysis indicated that BDNF levels were not significantly different between patients with epilepsy and control subjects, although patients with partial epilepsy are likely to have lower BDNF levels." (PMID 38707431, 2024). "Therefore, inhibition of BDNF/TrkB signaling and induction of neuropeptide Y (NPY) expression may reduce seizure frequency and severity in patients with epilepsy." (PMID 38006577, 2024). "However, dysregulation of BDNF in epilepsy is not a single entity but is related to the dysregulation of autophagy, mTOR pathway, PGN and α-Syn which negatively and positively regulate the BDNF/TrkB signaling pathway." (PMID 38006577, 2024). "Preclinical studies have shown that seizures can be suppressed by the overexpression of BDNF or GDNF in the hippocampus or cerebral cortex in animal models of epilepsy, suggesting that the lack of these NTFs may play a role in epileptogenesis." (PMID 39474368, 2024).
epilepsy (continued). "Preclinical studies that measure BDNF in epileptogenesis and induced epilepsy may not accurately reflect the level of endogenous BDNF as it is affected by different factors including age, sex and diurnal variations." (PMID 38006577, 2024). "In addition, luteolin stimulates brain-derived neurotrophic factor (BDNF) expression via the PKA/CREB/BDNF pathway, protecting neurons from oxidative stress and enhancing cognitive function in pentylenetetrazole (PTZ)-induced epilepsy." (PMID 39329119, 2024). "A relation between BDNF levels and severe forms of epilepsy has been proposed: BDNF levels could be a biomarker of the worsening epilepsy rather than a biomarker of epilepsy itself." (PMID 37923391, 2023). "However, similar to the previous data, the changes in levels of GDNF in LF and BDNF and cortisol in BS, assessed in the present study, did not depend on the etiology of epilepsy and were related to epilepsy in general, independent of its etiology." (PMID 38069144, 2023). "This may be related to a preventive effect on epilepsy, because the knockout (KO) of TrkB, but not BDNF, was confirmed in an epilepsy kindling model to completely block the development of epilepsy." (PMID 36065764, 2022). "Moreover, inhibiting BDNF-TrkB signaling and simultaneous activation of the NPY system could become a new treatment pathway for epilepsy." (PMID 33802323, 2021). "Therefore, it is proposed that the GR-encoding gene NR3C1 may participate in the pathogenesis of epilepsy by regulating BDNF, and NR3C1 is a possible shared gene for AD and epilepsy." (PMID 34697589, 2021). "Although studies that link BDNF with neuroinflammation in epilepsy are lacking, a hypothesis for such a link can be formulated based on existing knowledge." (PMID 30117106, 2019). "Finally, we focus on epilepsy, a pathology that highlights the links between GABA and BDNF." (PMID 30210299, 2018). "Increased expression of DPYSL5 can regulate dendritic development by mediating BDNF signaling in the central nervous system and modulate the function of CRMP2 by interacting with tubulin, thus affect the cytoskeleton remodeling, which is important in CCD with epilepsy." (PMID 28222113, 2017). "Thus, BDNF/TrkB signaling seems to be beneficial rather than harmful in epilepsy, and increasing BDNF level in epilepsy could be a compensatory mechanism to prevent seizure-induced neuronal injury." (PMID 38006577, 2024). "Thus, BDNF/TrkB signalling seems to be beneficial rather than harmful in epilepsy, and increasing BDNF levels in epilepsy could be a compensatory mechanism to prevent epileptic seizure‐induced neuronal injury." (PMID 37737447, 2023). "Therefore, we have not been able to determine whether this elevation of BDNF induces neuronal excitation to promote epilepsy, or it is simply a stressful increase of the body to repair neurons after the onset of epilepsy." (PMID 34899313, 2021). "Finally, the Mendelian randomization analyses relied on a small number of mQTLs (3 for epilepsy to BDNF methylation and 1 for methylation to epilepsy and other health outcomes) and therefore did not allow for sensitivity analyses aimed at ruling out bias due to horizontal pleiotropy." (PMID 31915053, 2020). "Overall results of the current study provide remarkable evidence of the ameliorative effect of chrysophanol in stress and without-stress PTZ-induced epilepsy through inhibition of the NFκB pathway and Regulation of VEGF/BDNF." (PMID 39650161, 2024). "Overall results of the current study provide significant evidence of the ameliorative effect of chrysophanol in stress and without-stress PTZ-induced epilepsy through inhibition of the NFκB pathway and Regulation of VEGF/BDNF." (PMID 39650161, 2024). "There are no data on the correlation between BDNF and the neurospecific proteins NSE, VILIP-1, and S100B, which reflect brain damage in epilepsy." (PMID 38203674, 2023).
epilepsy (continued). "BDNF and CNTF levels did not depend on the etiology of epilepsy, while GDNF level was higher in two PWE subgroups as compared with the “trauma” subgroup." (PMID 36142325, 2022). "In contrast to kindling and SE models of epilepsy, lack of effects on TMEV-induced seizures observed in pY816-treated and in BDNF+/− mice likely reflects model-specific differences in the mechanisms of ictogenesis." (PMID 35874836, 2022). "Comparison of ADORA2A rs2298383, BDNF rs6265, and NTRK2 rs1778929 diplotype distribution between childhood epilepsy (CE) patients with and without neurologic comorbidities." (PMID 33262686, 2020). "With the exception of the studies of IGF-1 in ANS dysfunction in Rett syndrome with epilepsy, the potential role of BDNF and IGF-1 in regulating ANS function and cerebral autoregulation in patients with epilepsy has not been reported." (PMID 30524358, 2018). "The BDNF to pro-BDNF ratio increases in kindled WT mice, but not in MMP-9 KO mice, during the progression of epilepsy implicating MMP-9 in pro-BDNF cleavage." (PMID 26283917, 2015). "Interestingly, our labs have shown that increased synthesis of proBDNF, and not mature BDNF, is the first response of the injured brain in the pilocarpine (PILO) model of epilepsy prior to SE-induced increases of p75NTR." (PMID 31455240, 2019).
bipolar disorder (229 papers, 2008 to 2026). A disorder of the brain that causes unusual shifts in mood, energy, activity levels and the ability to carry out day-to-day tasks. "The aim was to investigate cognitive subgroups in patients with bipolar disorder and their association with serum levels of BDNF and CRP." (PMID 41367212, 2025). "This is compatible with reports of BDNF decline as bipolar depression advances, and factors that increase trauma and life stress are also associated with decreased BDNF levels." (PMID 38500272, 2024). "Patients with bipolar disorders who carried the BDNF met allele exhibited smaller hippocampal volumes and scored lower on the cognitive scale compared to depressed patients and healthy controls." (PMID 38397229, 2024). "BDNF has also been associated with affective episodes and has been considered a potential differential marker between individuals with bipolar disorder and healthy controls." (PMID 38250270, 2023). "The yellow cluster is the smallest cluster and the main keywords are BDNF val66met, meta-analysis, bipolar disorders, biomarker, single nucleotide polymorphism (SNP), DNA methylation, prefrontal, and epigenetic." (PMID 37077958, 2023). "One study prospectively followed patients with bipolar disorder for 4 years and found that those with one or more BDNF Met alleles, indicating that decreased BDNF secretion produced a more significant reduction in LGI." (PMID 36684011, 2022). "In line with our findings a recent study reported higher levels of BDNF in bipolar disorder, where higher levels of BDNF were associated with longer illness duration." (PMID 35114967, 2022). "An investigation of 288 patients with bipolar disorder revealed that interaction between miR-206 and BDNF polymorphism increases the risk for bipolar disorder and treatment response to various drugs." (PMID 35916975, 2022). "In 2003, two research groups reported a significant association between the BDNF Val66Met polymorphism and bipolar disorder." (PMID 29867348, 2018). "For example, converging evidence suggests that BDNF is implicated in the pathogenesis of bipolar disorder." (PMID 29867348, 2018). "One of the main treatments for bipolar disorder, a mood stabilizer called lithium, has also been linked to BDNF in previous studies; however, the details of the interaction were not clear." (PMID 28621662, 2017). "In contrast, lithium treatment is associated with increased BDNF protein levels in the serum of patients with bipolar disorder." (PMID 28621662, 2017). "For example, BDNF methylation has been implicated in several psychiatric disorders, including bipolar disorder." (PMID 25788889, 2015). "Oxidative imbalance, alterations in brain-derived neurotrophic factor (BDNF), and mitochondrial dysfunction are implicated in bipolar disorder (BD) pathophysiology and comorbidities, for example, cardiovascular conditions." (PMID 26075103, 2015). "Literatures published and cited in Pubmed and Wanfang Data was searched with terms of ‘Val66Met’, ‘G196A’, ‘rs6265’, ‘BDNF’, ‘association’, and ‘bipolar disorder’ up to March 2014." (PMID 25539739, 2014). "Previous data from our group has found altered anterior cingulate volumes in individuals with bipolar disorder who carried the BDNF minor allele." (PMID 24944871, 2014). "Genetic studies have implicated this BDNF gene polymorphism in the risk for bipolar disorder, early disease onset, rapid cycling, suicidality associated with mood episodes, and treatment response." (PMID 25202283, 2014). "Only a single published study has reported that people with bipolar disorder who carried Met alleles at the BDNF Val66Met polymorphism were more likely to develop depressive episodes following stressful life events than Val allele homozygotes." (PMID 24860514, 2014). "Bipolar disorder has been underinvestigated, with only a single study showing an interaction between a functional polymorphism in the BDNF gene and stressful life events triggering bipolar depressive episodes." (PMID 24860514, 2014).